RNU6-430P (RNA, U6 small nuclear 430, pseudogene)
Gene: Small nuclear RNA gene on chromosome 16 (89,443,318 to 89,443,424, forward strand). Ensembl gene ENSG00000252887.
Homologues: Orthologues: chimpanzee U6 (97% identical), macaque U6 (91% identical), rat LOC120094986 (79% identical), mouse Gm26446 (73% identical), dog U6 (71% identical), pig U6 (66% identical). Paralogues in human: RNU6-16P (86% identical), RNU6-29P (86% identical), RNU6-41P (86% identical), RNU6-10P (85% identical), RNU6-393P (85% identical), RNU6-45P (85% identical), RNU6-639P (85% identical), RNU6-73P (85% identical), RNU6-921P (85% identical), RNU6-1131P (84% identical), RNU6-1145P (84% identical), RNU6-1152P (84% identical), and 1287 more.